MYC (MYC proto-oncogene, bHLH transcription factor)
Diseases named in the same sentence as MYC in open-access papers (continued):
Sharing a sentence is not in itself a finding about the gene and the disease.
breast cancer (continued). "Interestingly, chromosome 3 gain has not been observed in a BRCA1 driven murine breast cancer model, nor a KRAS driven model of non–small cell lung cancer while frequent partial gain of this chromosome was described in a MYC driven murine model of lymphoma." (PMID 29492199, 2018). "However, CDK4 gene regulation and its ability to respond to signals change in breast cancer cell lines, in which USF is transcriptionally inactive and CDK4 expression regulation independent of both USF and MYC." (PMID 28899340, 2017). "Kaplan–Meier analysis showed that the overall survival rates were significantly lower in breast cancer patients with than without amplification of one of these genes (log rank test; NDRG1, P = 0.0554; UBR5, P = 0.0122; MYC, P = 0.0094; EXT1, P = 0.0103; NBN, P = 0.0030; and COX6C, P = 0.0073)." (PMID 28977883, 2017). "On the other hand, we could not detect any correlation between the levels of MYC and PCAT-1 transcripts in the breast cancer tissues examined." (PMID 28989584, 2017). "Whether this also applies to other cancers is not known, and we therefore quantified MYC and NDRG2 mRNA in a set of breast cancer samples." (PMID 21226903, 2011). "Interestingly, although glutamine metabolism is independent of estrogen in aromatase inhibitor-resistant breast cancer, the cross-talk between ER and HER2 upregulates the c-MYC pathway and further increases the expression level of GLS, SLC1A5, and glutamine consumption." (PMID 36077501, 2022). "Additionally, the cut-off for c-MYC ‘positivity’, selected based on parameters for HER2 FISH testing in breast cancer, may not have been set sufficiently high enough to overcome this therapeutic hurdle." (PMID 35448150, 2022). "Results from studies in different organ-type cancers including breast cancer indicated that CIP2A, rather than independently/ exclusively accomplishing the tumorigenic effect in cells, forms an important component of the “oncogenic nexus” in concert with PP2A and c-MYC." (PMID 25015035, 2014). "In ER+ breast cancer we observed that high MYC synergized with high RAS activation to provide a better prognostic stratification than either high MYC or high RAS alone, and that this non-linear MYC-RAS interaction added prognostic value over the single-pathway models." (PMID 21050467, 2010).
lymphoma (1,054 papers, 2003 to 2026). A malignant (clonal) proliferation of B- lymphocytes or T- lymphocytes which involves the lymph nodes, bone marrow and/or extranodal sites. "This evidence suggests that MYC upregulation is a driver event in lymphoma development and maintenance, and this is often linked to the pro-proliferative phenotype typically induced by MYC aberrant expression/activity." (PMID 41008653, 2025). "Most MYC mutations display characteristics consistent with aberrant somatic hypermutation, a hallmark of GC-B cell-derived lymphomas." (PMID 40067847, 2025). "Even if MYC dysregulation in lymphomas is mostly associated with chromosomal translocations and, to a lesser extent, copy number gains, MYC point mutations represent another type of MYC alteration, which have been firstly observed in BL." (PMID 41008653, 2025). "The concentration of virus sequences around MYC on chromosome 8 prompted the addition of the EBV-associated lymphoma DLBCL to breakpoint comparisons." (PMID 39885374, 2025). "Burkitt’s lymphoma is characterized by the overexpression of c-MYC, which is implicated in the pathogenesis of Burkitt’s lymphoma and other lymphoma subtypes." (PMID 40308579, 2025). "Aside from chromosomal rearrangements, MYC deregulation in lymphomas is also caused by other genetic alterations such as MYC copy number gains." (PMID 41008653, 2025). "MYC overexpression via enhancer hijacking is the hallmark of several lymphoid cancers, particularly Burkitt Lymphoma." (PMID 41152984, 2025). "Because MYC gene rearrangements are characteristic of EBV-associated lymphomas, the first test of this idea was to survey virus-like sequences surrounding the MYC gene locus on the human reference genome." (PMID 39885374, 2025). "In Burkitt lymphoma, MYC rearrangement with one of the IG gene loci is a genetic hallmark of this lymphoma." (PMID 39594704, 2024). "PICH is overexpressed in various human cancers, particularly in lymphomas such as Burkitt lymphoma, which is caused by MYC translocations." (PMID 38253636, 2024). "Meanwhile, MYC, a transcription factor and oncogene, is implicated in various cancers, including lymphomas, and is associated with aggressive clinical behavior." (PMID 39469218, 2024). "Collectively, these findings demonstrate Arrdc3 loss leads to a marked acceleration of MYC-driven lymphoma development." (PMID 38097622, 2024). "In lymphomas, MYC activation occurs through mutation, amplification, translocation, and various other molecular processes." (PMID 39464313, 2024). "We then monitored those mice possessing an Eμ-Myc transgene to determine the impact of Arrdc3 loss on MYC-driven lymphoma development." (PMID 38097622, 2024). "Based on this data, our cases with 3’MYC signal loss should be excluded from the “double-hit” lymphoma category." (PMID 38903717, 2024). "We have observed that PICH deficiency delays the onset of MYC-induced lymphomas in Pich heterozygous females." (PMID 38253636, 2024). "A subtype of lymphomas is called a double-hit lymphoma, which forms when it contains MYC and either BCL2 or BCL6 mutations; this subtype is often seen in patients who have disease at the interference between Burkitt lymphoma and DLBCL." (PMID 39010207, 2024). "Double-hit or triple-hit lymphomas, where there are chromosomal translocations involving MYC, BCL2 and/or BCL6 oncogenes, are associated with a higher risk of CNS recurrence." (PMID 38173015, 2024). "In follicular lymphoma, up to 75% of histological transformations to a high-grade lymphoma (t-FL) show MYC mutations/translocations/amplification or gains associated with MYC overexpression and other alterations." (PMID 39594704, 2024). "It is worth noting that double-expressor lymphomas that overexpress MYC and BCL2 proteins are aggressive DLBCLs and are associated with a dismal prognosis." (PMID 39518937, 2024).
lymphoma (continued). "Data on the association between the expression of intracellular MYC and cell surface immune checkpoint molecules are conflicting in lymphoma." (PMID 39596160, 2024). "To elucidate the contribution of loss of TFAP4 to c-MYC-driven lymphoma development we compared the expression of genes within certain hallmarks of cancer pathways that TFAP4 has been reported to regulate." (PMID 36894688, 2023). "General targeting of SEs with BRD4 inhibitors has shown efficiency, in particular in cancers with specific SE single mutation alterations or with the activation of MYC SE in leukemia or lymphoma." (PMID 36944729, 2023). "Transgenic mice overexpressing MYC alleles in lymphoid or myeloid cells develop lymphoma or leukemia." (PMID 36969025, 2023). "We intentionally used a catalog derived from MYC‐driven B‐cell lymphomas due to the exceptional load of DNA damage caused by activated MYC signaling in these lymphomas." (PMID 37485814, 2023). "The oncogenic transcription factor MYC plays extensive roles in cancers including lymphoma, and its deregulation is associated with lymphoma progression and poor prognosis." (PMID 38007476, 2023). "Drugs based on Rocaglates have been gradually applied in treatment of lymphomas with MYC mutations, with promising therapeutic value." (PMID 36812125, 2023). "Due to its very restricted expression, targeting DDX3Y in lymphoma patients harboring an activated c-MYC allele in addition to a DDX3X LOF is very likely the best strategy." (PMID 37035206, 2023). "Both regions contain candidate genes with known lymphoma-associated annotations which are linked to the oncogenic effects of the MYC gene, amongst other functions." (PMID 38133254, 2023). "On a genetic level, these lymphomas show frequent gains of 8q24 (including MYC gene) and recurrent mutations of STAT5b, JAK3, GNAI2, and SETD2." (PMID 37345080, 2023). "First studies presented, that this lymphoma, which morphologically and phenotypically resembles Burkitt lymphoma (BL), has unique chromosome 11q aberrations (11q gain/loss) instead of MYC rearrangement." (PMID 37941034, 2023). "STAT3 and STAT6 have lymphoma-promoting properties due to their activation of genes encoding for proteins such as MYC, BCL-XL and CYCLIND1." (PMID 36671496, 2023). "To assess the specific role of AID in MYC-driven lymphomagenesis, we combined the λ-MYC lymphoma model with the AicdaCre+/ki and R26tdTom+/ki alleles." (PMID 37809061, 2023). "Of note, the combined loss of PUMA, NOXA, and BIM renders MYC-driven lymphoma cells almost completely resistant to killing by DNA damage inducing anti-cancer agents, such as etoposide or cyclophosphamide." (PMID 36342579, 2023). "In particular, recent multi‐omic studies in CLL identified MYC activity as one of the main features associated with morbidity, either within the chronic phase or during the evolution to high‐grade lymphoma (a process known as Richter transformation)." (PMID 36214609, 2022). "LncRNA GAS5 interacts with translation initiation factor eIF4E and inhibits the translation of MYC gene that encodes c-Myc in lymphomas." (PMID 36010595, 2022). "The mechanism of TRIB3 has been investigated; previous studies have shown that TRIB3 promotes MYC-associated lymphoma development through suppression of UBE3B-mediated MYC degradation." (PMID 35726370, 2022). "Mutation of MYC in lymphomas is frequently linked to IGH translocations, which nevertheless are rare in the PCNSL as shown in the present as well as previous studies." (PMID 35538064, 2022). "This miRNA is a component of the miR-17-92 cluster on chromosome 13q31.3, which is activated by the MYC proto-oncogene and is commonly amplified in various solid tumors and lymphomas and associated with a malignant progression of MM." (PMID 36499093, 2022).
lymphoma (continued). "In vivo, loss of CDK2 makes pancreatic cells and splenic B-cells more susceptible to MYC-induced senescence, which coincides with a delayed beginning of lymphoma in the latter." (PMID 35408915, 2022). "eFT226 also caused a G1 cell cycle arrest in lymphoma cell lines due to the inhibition of translation of MYC, CDK4 and cyclin D1, which led to anti-tumor activity in vivo." (PMID 34398253, 2021). "For example, somatic SNV clustering within intron I of MYC has long associated with its upregulation in lymphoma." (PMID 33554123, 2021). "On the other hand, the p.N26S mutation in MYC is oncogenic; it has been identified in lymphomas and prostate cancer as well as lung cancer." (PMID 34198671, 2021). "This would thus be one way to account for the common occurrence of reduced-activity mutations such as T58I in lymphomas, particularly those such as Burkitt’s lymphoma, where MYC activation is known to be the primary driver." (PMID 34885204, 2021). "Two lymphoma-associated MYC mutants (resulting in the substitution of threonine 58 with isoleucine, T58I, or alanine, T58A) were also analyzed and compared with each other and wild type MYC." (PMID 34885204, 2021). "We studied the changes in transcriptional programs as MYC levels were progressively increased, causing a simultaneous transition to a lymphoma cell phenotype." (PMID 34885204, 2021). "Further studies utilizing CG-806 in combination with venetoclax show inhibition of driver and rescue pathways within in-vivo studies using double/triple hit lymphoma cell lines that harbor MYC/BCL2/BCL6 mutations, yielding promising results." (PMID 34829820, 2021). "The loss of IL-6 in MYC lymphomas also leads to a compensatory increase in proteins expressed in the mTOR pathway." (PMID 33651821, 2021). "It is important to note that in lymphoma, mutations of T58 are observed in the context of MYC proteins that are over-expressed due to genetic rearrangements." (PMID 34885204, 2021). "The role of MYC in causing lymphoma was further demonstrated in B-cell and rarely in T-cell lymphoma." (PMID 34372899, 2021). "Eμ-myc mice typically develop aggressive B-cell lymphomas at an early age, and loss of IL-6 delayed the development of these MYC-driven lymphomas." (PMID 33651821, 2021). "Instead, it is MCL-1 which appears to be the key factor driving the sustained growth of Eμ-MYC lymphoma and even the loss of a single allele was enough to lead to complete regression in 20% of tumours." (PMID 33799592, 2021). "We examined c-Myc protein levels in two lymphoma cell lines in which genomic translocations of IgH with c-MYC have resulted in loss of the c-MYC promoter, either retaining or losing the G4-quadruplex (Raji and CA46, respectively)." (PMID 33303632, 2021). "We conclude that CXCR4 activation is an integrative hallmark of aggressive MYC-driven lymphoma, and show that MYC translocation and MYC expression correlate with increased CXCR4 expression." (PMID 34363012, 2021). "More critically and consistent with the observed aggressive tumor phenotype, Smc3/Bcl6 lymphomas featured induction of canonical GC-associated MYC target gene sets." (PMID 34621263, 2021). "We also explored the expression of lymphoma-associated markers including CD markers, cytotoxic molecules, and MYC protein." (PMID 32587329, 2020). "These mutations are likely to be functional, pathogenic and selected during lymphoma development as they affect the phosphorylation site (T58) and its neighbouring amino acids, which are important for MYC protein degradation." (PMID 31844144, 2020). "We have uncovered therapeutically actionable mutations in the JAK/STAT, MAPK, MYC, and chromatin modifying pathways in both Vδ1 and Vδ2 lymphomas." (PMID 32286303, 2020).
lymphoma (continued). "Mechanistically, TRIB3 interacts with MYC to suppress E3 ubiquitin ligase UBE3B-mediated MYC ubiquitination and degradation, which enhances MYC transcriptional activity, causing high proliferation and self-renewal of lymphoma cells." (PMID 33298911, 2020). "The development of novel techniques in the field of immunology and new animal models has greatly accelerated our understanding of oncogenic mechanisms in MYC-associated lymphomas." (PMID 32549409, 2020). "Here, we studied the impact of loss of RIPK3 in a mouse model of MYC-driven lymphomagenesis and on the killing of malignant lymphoma cells induced by chemotherapeutics." (PMID 32555451, 2020). "Deregulation of MYC is a pervasive finding in lymphoma that causes tumor progression and a poor prognosis, and MYC is obviously a good therapeutic target in lymphoma." (PMID 33298911, 2020). "TRIB3 knockout suppresses the cell proliferation and self-renewal ability of MYC-associated lymphoma by reducing MYC protein stability and abundance in these cells." (PMID 33298911, 2020). "MYC expression in DLBCL increases lymphoma aggressiveness and is associated with a poorer clinical prognosis." (PMID 32753663, 2020). "When the expression of MYC protein is aberrantly altered, the risk of developing a hematological malignancy, such as leukemia or lymphoma, increases substantially through the acquisition of an uncontrolled proliferative rate and a blockade of differentiation." (PMID 32102485, 2020). "Substantial evidence 37 of both in vitro and in vivo models have provided that MYC prompts many genes that involved in ribosome biogenesis including genes associated in glucose and glutamine metabolism to accommodate the growing lymphoma cells." (PMID 31892985, 2020). "Development of novel techniques in the field of immunology and new animal models have greatly accelerated our understanding of oncogenic mechanisms in these MYC-associated lymphomas." (PMID 32549409, 2020). "The mutations were more frequent in double-hit lymphomas with IG as the MYC translocation partner, and were associated with higher MYC protein expression and poor patient survival." (PMID 31844144, 2020). "Whereas the activation of MYC in lymphomas is partially caused by an elevated mutation frequency in several cases, B-cell precursor leukemia has an almost negligible mutation rate." (PMID 32102485, 2020). "Loss of one MCL-1 allele almost abrogated MYC-driven-lymphoma development owing to a reduction in lymphoma initiating pre-B-cells." (PMID 32549409, 2020). "In lymphoma cells, miR-17-92 regulates MYC mRNA levels through the inhibition of Chk2, causing the depression of RNA-binding protein HUR, and its binding to MYC mRNA, preventing MYC translation." (PMID 30987378, 2019). "Consistent with the enforced expression of BCL2 and MYC, we saw strong enrichment for signatures of double hit lymphoma, a subtype of lymphoma characterized by translocation of both MYC and BCL2 and associated with a particularly poor clinical outcome." (PMID 31586074, 2019). "Chromosomal translocations involving MYC gene were identified in lymphoma in the early 1980s, and aberrant MYC expression is frequently associated with disease progression and poor clinical outcome." (PMID 31311566, 2019). "In contrast to other genetic alterations (copy number variations, chromosomal translocations, increased enhancer activity), MYC gene mutations are uncommon, but have been described in some cancers (e.g. lymphomas)." (PMID 29324814, 2018).